LILRP2 (leukocyte immunoglobulin-like receptor pseudogene 2)
Synonyms: ILT10; CD85m
Gene: Transcribed processed pseudogene on chromosome 19 (54,708,602 to 54,713,232, forward strand). Ensembl gene ENSG00000170858.
Diseases named in the same sentence as LILRP2 in open-access papers:
LILRP2 is named in the same sentence as 1 disease in open-access papers, as found by Europe PMC text mining. Sharing a sentence is not in itself a finding about the gene and the disease. The quoted sentences say what the papers report.
oesophagitis (1 paper, 2021). "The inflammation-related variants associated with oesophagitis were rs4772468 at FGF14 (associated with increased risk) and rs270771 at LILRP2 (associated with decreased risk)." (PMID 33810047, 2021).